AGO2 (argonaute RISC catalytic component 2)
Diseases named in the same sentence as AGO2 in open-access papers (continued):
Sharing a sentence is not in itself a finding about the gene and the disease.
tumor (continued). "Work from Sheng’s laboratory has shown that LSD1, through demethylation of AGO2 (Protein Argonaute 2) has a crucial role in the suppression of anti-tumor immunity and tumor immunogenicity." (PMID 30866496, 2019). "Together these point to a role for Ago2 (either directly or indirectly) in promoting or regulating tumour growth." (PMID 31324173, 2019). "We observed that miR-145-5p downregulation was accompanied by a reduction also of Ago2 protein level in tumor tissues compared to the normal counterparts." (PMID 30622242, 2019). "However, as restoration of tumor suppressor miRNA levels has been proposed recently as a promising therapeutic intervention to cure diverse cancers, our study underlines how information about Ago2 protein expression level becomes crucial for the success of these novel therapeutic approaches." (PMID 30622242, 2019). "A previous study reported that AGO2 up-regulation by resveratrol enhanced the expression of some tumor-suppressive miRNAs and increased its RNA interference activity." (PMID 29872500, 2018). "The correlations of protein expression of Drosha, AGO1 and AGO2 with sex, age, tumor stage, histological grading and overall survival were evaluated in order to identify their diagnostic and prognostic potential in urothelial cancer." (PMID 29857476, 2018). "A previous study reported that resveratrol induces some tumor-suppressive miRNAs and Argonaute 2 (AGO2) expression, which can result in long-term gene silencing." (PMID 29872500, 2018). "The exosomes delivered by tumor cells contain both miRNAs and proteins/enzymes (Dicer, Argonaute 2 (Ago2) and TRB as well as the RISC Complex) used for miRNAs processing and silencing the mRNA targets of the recipient cells." (PMID 30469518, 2018). "Knockdown of AGO2 can inhibit cell proliferation and tumor growth, decrease cell migration and invasion, arrest cell cycle and induce apoptosis." (PMID 28903378, 2017). "The levels of FAK were up-regulated in tumor tissues (P<0.0001), in accord with AGO2 expression pattern in the distinct tissues." (PMID 28903378, 2017). "The mechanisms of Ago2 upregulation and its repercussions in tumor brain and chemo brain need to be further studied." (PMID 29179434, 2017). "miR-99a appears to be a tumor suppressor in the liver that possibly acts through inhibition of the RNA-induced silencing complex, Ago2." (PMID 28174625, 2017). "Although knockdown of AGO2 has been proved to inhibit cell proliferation and tumor growth, the intrinsic molecular mechanisms are still unclear." (PMID 28903378, 2017). "Meanwhile, tumor cell migration and invasion abilities were also significantly inhibited in vitro in FaDu cells after down-regulation of AGO2 expression (P<0.001)." (PMID 28903378, 2017). "Our investigations identified that miR-92b-3p levels were significantly elevated in exosomes than in Ago2-positive fractions of SS-patient serum, indicating that this miRNA circulates in SS patients and is loaded on tumour-derived exosomes." (PMID 29116117, 2017). "While we did not see any changes in the Dicer levels, we noted a significant upregulation in the levels of Ago2 in the PFC tissues of PR+BC tumor-bearing treated and untreated animals." (PMID 29179434, 2017). "Recent reports have demonstrated that they exist with remarkable stability in body fluids as cell-free miRNA that originates from primary tumour cells embedded within tumour-derived exosomes or argonatute-2 (Ago2)." (PMID 29116117, 2017). "Since previous studies indicate that HIF-2α promotes the growth, invasion, and angiogenesis of tumor cells, we further investigated the effects of miR-558 over-expression and knockdown of AGO2, eIF4E, or HIF-2α on cultured NB cells." (PMID 27276678, 2016). "EGFR induces phosphorylation of Y393 in AGO2 to inhibit miRNA maturation, leading to tumor cell survival." (PMID 27701455, 2016).
tumor (continued). "With regard to NPC, the elevated mRNA expressions of AGO2 were observed in tumor tissues and latent membrane protein 1 (LMP1)-positive tumors compared with normal adjacent nasopharyngeal epithelium tissues and LMP1-negative tumors, respectively." (PMID 26545861, 2015). "There is also evidence suggesting that AGO2, in response to hypoxia, is differentially regulated in tumor and smooth muscle cells, which in turn modulates the maturation of various miRs and influences downstream gene expressions." (PMID 26588727, 2015). "EGFR restrains the maturation of specific tumor suppressor miRNAs, such as miR-31, -192, and miR-193a-5p, by phosphorylation of Argonaute 2 (AGO2) at Tyr393." (PMID 26287249, 2015). "AGO2 binds to the tumor metastasis factor focal adhesion kinase promoter and triggers its transcription, which suggests a new function of AGO2 in tumor progression." (PMID 24904827, 2014). "The majority (97%) of miRNAs of tumour origin circulate in the blood in complexes with Ago2, which are very stable and protect miRNAs from degradation, similar to small membranous vesicles." (PMID 24386211, 2013). "While our studies were not designed to conclusively resolve the role of Ago2 as oncogene or tumor-suppressor, we also noted a spectrum of cellular phenotypes among our initial Ago2 cell lines." (PMID 24049077, 2013). "Our previous studies demonstrated that circZNF609 can bind to AGO2, suggesting that the tumor‐suppressive function of circPCSK6 may diverge from the canonical ceRNA paradigm." (PMID 39836545, 2025). "Consequently, AGO2 binding decreased, AGO2 miRNA-mediated gene silencing was suppressed, and tumor formation and invasion increased." (PMID 39077467, 2024). "We grew HCT116 cells in a collagen matrix to form tumor spheroids to test whether the nuclear localization of AGO2 would be affected in culture conditions that better represent characteristics of human tumors." (PMID 38109320, 2024). "Ago2 differentially regulates oncogenic and tumor-suppressive miRNAs in cancer cells." (PMID 38649663, 2024). "Ago2 also differentially regulates oncogenic and tumor-suppressive miRNAs in cancer cells." (PMID 38649663, 2024). "In addition, blocking Ago2/CAV1 interaction in HCC1806Ago2-KO/AID-Ago2Wt/Ago2∆ cells decreased primary tumor cell dissemination to lymph nodes by 86% (Fig. 5Fiii) and to the lungs by 84% (Fig. 5Fiv)." (PMID 38649663, 2024). "The tumor samples yielded different outcomes for the nuclear localization of AGO2." (PMID 38109320, 2024). "We next investigated whether blockage of Ago2/CAV1 interaction affects the metastatic tumor formation of circulating cancer cells in organs." (PMID 38649663, 2024). "Strikingly, metastatic H1299 tumor nodules were found on the CAM in the presence of Ago2 and ΔNp63." (PMID 35459267, 2022). "It will be intriguing to determine if there are any differences in the levels of AGO2 and dsRNAs between human tumor cells with and without loss of mutations in MLL4." (PMID 36323669, 2022). "Furthermore, Ago2 ablation in a mutant Kras-driven nonsmall cell lung cancer (NSCLC) mouse model significantly reduced tumor burden and altered downstream Kras signaling." (PMID 35923912, 2022). "Ago2 exhibits a dual function regulatory role in tumor progression." (PMID 35459267, 2022). "Re-introduction of exogenous Ago2 partially rescues tumor growth defects in immunocompetent mice." (PMID 36323669, 2022). "Mechanistic studies with epigenetic and transcriptomic profiling showed that MLL4 promotes activation of both typical and super enhancers to increase the expression of their nearby genes, including the RISC component Ago2 and the DNA methyltransferases Dnmt1 and Dnmt3a in tumor cells." (PMID 36323669, 2022).
tumor (continued). "KDM1A also demethylates Ago2 at the K726me1 site to regulate the tumor T cell response." (PMID 34307695, 2021). "Many studies have focused on the role of AGO2 in tumorigenesis and tumor progression." (PMID 33846300, 2021). "We speculate that modulating Ago2 levels may also regulate tumorigenesis by altering the activities of specific miRNAs (e.g., the tumor-suppressive let-7 miRNAs)." (PMID 33599613, 2021). "Cytosolic MSI1 engages AGO2 to promote stress-induced tumor growth through RNA regulation." (PMID 31903115, 2020). "Mice bearing AGO2−/− xenografts showed decreased tumor sizes and delayed tumor progression." (PMID 32420319, 2020). "In cancer patients, miRNAs are abundant as circulating molecules: actively secreted by tumor cells into exosomes, passively released in the extracellular space bound to the Argonaut 2 protein (Ago2), or as free molecules derived from apoptotic or necrotic tumor cells." (PMID 32726984, 2020). "In contrast, we observed the opposite effect in MSI1- and AGO2-knockdown cells, suggesting that MSI1/AGO2 complex could stabilize in response to stress a subset of mRNA targets related to cell cycle (group 1) to subsequently promote tumor progression." (PMID 31903115, 2020). "Concomitantly, in vivo studies showed that AGO2 knockdown abolished the MSI1-enhanced tumor growth." (PMID 31903115, 2020). "The disruption of MSI1/AGO2 interaction with decoy peptides efficiently inhibits tumor growth, suggesting that peptide-based therapy could be of importance to decrease recurrent GBM and PDAC." (PMID 31903115, 2020). "Importantly, overexpression of the C-terminus of MSI1 disrupts endogenous MSI1/AGO2 interaction and effectively reduces stress-induced tumor progression." (PMID 31903115, 2020). "Using GeneMANIA (Multiple Association Network Integration Algorithm) for prediction of gene function, Liu and colleagues revealed that AGO2 upregulation was correlated with acceleration in tumor progression and poor survival in a cohort of 962 lung-cancer patients." (PMID 32503341, 2020). "Collectively, our results indicated that the cytosolic MSI1/AGO2 complex interaction and downstream pathway was significantly enhanced in patients with tumor relapse and could affect patient survival." (PMID 31903115, 2020). "Additionally, the phosphorylation status of LASP1 affected tumor suppressor microRNA (miRNA) Let-7a-guided Ago2 activity." (PMID 32872485, 2020). "Notably, overexpression of MSI1 C-terminus increased sensitivity to chemotherapeutic drugs, thus hindering the malignant progression of GBM, which opens the possibility to treat tumor recurrence via tackling the MSI1/AGO2 complex formation." (PMID 31903115, 2020). "In tumours Ago2 mRNA expression correlated with reduced relapse free survival." (PMID 31324173, 2019). "Especially, tumors in the AGO2-WT-pre-miR-19b1 group exhibited distinct promotion of growth compared to those in the control vector, AGO2-WT, or pre-miR-19b1 group, indicating that the increased miR-19b mediated by AGO2 acetylation leads to the tumor growth." (PMID 30305728, 2019). "To understand whether miR-143 delivered by PIC inhibited tumor growth through RNAi, we performed an Argonaute2 (Ago2) loading assay." (PMID 30911586, 2019). "Induction of Ago2 protein is necessary to allow miR-145-5p tumor suppressor function." (PMID 30622242, 2019). "However, tumors in the AGO2-3KR or AGO2-3KR-pre-miR-19b1 group grew much more slowly than those in the AGO2-WT or AGO2-WT-pre-miR-19b1 group, respectively, suggesting the acetyl-mutant AGO2-3KR lost its function in promoting tumor growth." (PMID 30305728, 2019).
tumor (continued). "Future work should explore Ago2 expression levels in the tumour samples with gene amplification." (PMID 31324173, 2019). "Further work to investigate this potential new role could reveal additional core roles of Ago2 that impact on tumour progression." (PMID 31324173, 2019). "We also performed the Ago2 loading assay to examine whether miR-143/PIC suppressed the tumor growth through RNAi in the tumor cells." (PMID 30911586, 2019). "Furthermore, the miRNA independent role of Ago2 in regulating the transcription of the tumour metastasis factor focal adhesion kinase (FAK), suggests another role for Ago2 in mediating tumour progression." (PMID 31324173, 2019). "With concern to Ago2 function, Ago2 has been related to miRNA-dependent tumor suppression as well as to pro-tumoral functions, and the level of expression of specific miRNAs may be an important determinant for Ago2 function." (PMID 30622242, 2019). "Overall these results indicate that miR-145-5p exerts its tumor suppressor function in cells expressing Ago2 protein and suggest that Ago2 protein might contribute to the choice of targets by miR-145-5p." (PMID 30622242, 2019). "Additional examples of RBPs with known oncogenic or tumor suppressive functions that have been linked to EV miRNA sorting include Annexin A2 (ANXA2), Kirsten rat sarcoma (KRAS), Y-box binding protein 1 (YB-1), MEX3C, and Argonaute 2 (AGO2)." (PMID 30071693, 2018). "Since miRNA/Ago2 complexes as well as miRNA in the microvesicles are known to participate in the distant (similar to endocrine) regulation we observed global changes in miRNA profiling and whole transcriptome of tumor tissue." (PMID 29108266, 2017). "Furthermore, a 5′RACE assay on the RNA extracted from the treated xenograft tumour suggests specific survivin mRNA cleavage at the expected siRNA cut site through the Argonaute2 (Ago2) mechanism." (PMID 28724889, 2017). "Increased AGO2 expression was associated with a negative clinical outcome for ERα+ but not for ERα− tumor types." (PMID 29657266, 2016). "For example, EGFR could suppress the maturation of specific tumor-suppressor miRNAs in response to hypoxic stress through phosphorylation of argonaute 2 (AGO2)." (PMID 26646588, 2016). "The single-stranded RNAi-CK2 oligomer employed by us may be inducing miRNA-like translational repression mechanisms in the tumor cells consistent with the robust expression of Ago1 relative to Ago2 in the xenografts." (PMID 27557516, 2016). "However, AGO2 has significant roles controlling the tumorigenesis and progression of several cancers, including tumor invasion and metastasis." (PMID 26545861, 2015). "Hitherto, the role of AGO2 in tumour biogenesis has been unclear." (PMID 24886719, 2014). "Unfortunately, DGCR8 and AGO2 mRNA expression levels were not statistically associated with age, tumor stage (TNM), CEA titer, and BMI clinical parameters in our CRC specimens." (PMID 23775303, 2014). "For example, the tumor suppressor miRNAlet-7 could target Lin-41, whose function is to regulate the ubiquitylation anddegradation of Ago2; this change thus leads to a high tumor grade and a high tumorstage." (PMID 25012758, 2014). "AGO2 may play a role in double-strand break repair in tumour cells." (PMID 37353728, 2023). "Thus, ΔNp63 may induce a highly malignant transformation of Ago2 function and contribute to tumor dissemination." (PMID 35459267, 2022). "Contrary to the tumor microenvironment, almost all miRs in plasma of healthy donors could be immunoprecipitated by AGO2 antibodies, suggesting that the majority of plasma-borne miRs are associated with non-exosomal fraction and are free to interact with anti-AGO2 antibodies." (PMID 35562884, 2022). "Moreover, YTHDF2 could also accelerate the degradation of YAP mRNA through the Argonaute 2 (AGO2) system, inhibiting the growth and metastasis of tumor cells to diminish disease progression." (PMID 35382893, 2022). "Therefore, MSI1/AGO2 pathway promotes stress-induced tumor growth." (PMID 32448364, 2020).